IFNG (interferon gamma)
Diseases named in the same sentence as IFNG in open-access papers (continued):
Sharing a sentence is not in itself a finding about the gene and the disease.
malaria (continued). "Analysis of basal IFNγ production according to the CD56dim or CD56bright phenotype confirmed that in both acute malaria and in severe malaria subjects, the CD56NKbright population produced significantly higher levels of cytokine (p < 0.0001) than the CD56dim population." (PMID 22316273, 2012). "TNFα and IFNγ producing CS-specific CD4+ T cells were at much lower frequencies among control vaccinees, but nevertheless were associated with reduced risks of clinical malaria of borderline significance." (PMID 21998698, 2011). "Previous studies showing marked IFNγ production have been done in adults, and IFNγ production may be suppressed in children in malaria endemic areas." (PMID 21998698, 2011). "A role for IL-10-producing inducible regulatory T cells and/or IL-10/IFNγ-producing Th1 cells identified in P. yoelii-infected mice and malaria patients, respectively, may also contribute to this latter process." (PMID 21170302, 2010). "Interestingly and in line with our findings, Treg frequencies determined by Foxp3 mRNA levels were recently shown to negatively correlate with the magnitude of malaria-specific memory IFNγ responses in human malaria patients." (PMID 19680449, 2009). "In this context it was recently shown that effector T cells co-producing IFNγ and IL-10, which are more prevalent in children with mild than severe malaria, may help to regulate acute malarial inflammation." (PMID 19680449, 2009). "Chronic infection with malaria parasites has been associated with immunosuppressive responses to the parasite and to unrelated antigens.In animal models of malaria, the release of interferon gamma (IFN-γ) has been shown to mediate protection when secreted by Plasmodium specific CD8 or CD4 T-cells." (PMID 20037644, 2009). "Moreover, an ethnic group in West Africa, the Fulani, shows a functional deficit in Treg related gene expression, as well as elevated levels of peripheral blood malaria-specific Th1 (IFNγ) and Th2 (IL-4) producing cells." (PMID 19680449, 2009). "Whether IFNγ, TNFα and IL-10 regulate the self-reactive antibody response during malaria, as is the case for primary biliary cirrhosis, remains to be shown." (PMID 17460756, 2007). "Befitting any general immune response mechanism, various cytokines may potentially modulate ICAM1 expression, of which we have found evidence for statistical association of IL1, IL4 (and its receptor, IL4R), IL6, IL13, TLR2, TLR4, and IFNG (and its receptor, IFNGR1) polymorphisms with malaria." (PMID 37287037, 2023). "We speculate that this balance of Ab-mediated activation may be beneficial, as excessive secretion of pro-inflammatory cytokines, such as IFNγ and TNFα, in the placenta of malaria-infected women, especially in primigravidae, has been associated with placental pathology and adverse clinical outcomes." (PMID 33602987, 2021). "However, the frequency of CD4 cells producing IL10 but not inflammatory cytokines (IFNγ and TNFα) was associated with a decreased risk of clinical malaria once infected." (PMID 29097996, 2017). "A population of monofunctional CD8+ T cells, positive for IFNγ, but not for IL-2 or TNFα, previously found associated with delay to patency following controlled human malaria infection of malaria-naïve adult volunteers using this vaccine was detected in all three infant groups." (PMID 29213269, 2017). "The differences we observe in this study between G2–4 and G5–7 women's responses may reflect a shift from a more marked macrophage inflammatory response to a greater role for IFNγ-mediated responses in women with a greater history of exposure to malaria in pregnancy." (PMID 24465935, 2014). "Further studies are required to investigate the age-dependent induction of other regulatory cell responses during malaria, such as Tr1 CD4 T cells which co-produce IL10 with IFNγ and dominate the CD4 T cell compartment during malaria infection." (PMID 41027884, 2025).
malaria (continued). "Another study found that interferon gamma (IFNγ) and tumor necrotic factor alpha (TNF-α) levels are lower in pregnant women who have both malaria and HIV infections." (PMID 36692923, 2023). "Infection studies in animals have shown that malaria infected hepatocytes produce type I IFN, and IFNγ-secreting NK and NKT cells are recruited as liver stage parasites are eliminated." (PMID 35108339, 2022). "Among the top 50 genes identified in our RNA-Seq experiment, 5 of them (IFNG, CXCL8, IL3RA, SNX10, MYOF, and RSAD2) had promoter regions that were significantly more accessible in convalescent child patients with malaria than in adult convalescent patients." (PMID 35642634, 2022). "It has also been found that individuals with greater malaria disease severity had higher levels of CRP, TNFα, and IFNg." (PMID 33731158, 2021). "Our data indicate that Kupffer cells/macrophages are the predominant source of Gal-9, Tim-3, IFNα, IFNβ, IFNγ, and TREM-1, and play an important role in the liver damage during the erythrocytic stage of malaria induced by PbANKA infection." (PMID 34899708, 2021). "In the malaria-exposed volunteers, numbers of IL5- and IFNγ-secreting cells increased following vaccination, unexpectedly this increase appeared to be more pronounced in the Saline group." (PMID 33854065, 2021). "Studies in malaria-endemic countries have found that it is crucial to have a balance between a host pro-inflammatory, Th1 response (e.g., TNF, IL-6, IL-12, and interferon-gamma) and anti-inflammatory, Th2 response (IL-4, IL-10, and others)." (PMID 33357220, 2020). "Within the malaria pathway, miR-146a suppresses the CD40L, CXCL8, IFNγ, TLR2, TLR4, and ITGβ2 genes." (PMID 29747626, 2018). "Finally, the increased expression of interferon-gamma (XP_001377372.1) and interleukin 2 receptor (NP_990, 197.1) represent potentially important immune responses given that these are critical elements of the resting memory of malaria-exposure in memory T-cells in humans." (PMID 30518325, 2018). "Nevertheless, the depletion of IFNγ-producing cells resulted in decreased RTS,S-mediated protection in a malaria challenge model, accompanied by a decreased CSP-specific CD4+ T-cell response and limited effects on protective antibodies." (PMID 29263880, 2017). "Similar results were obtained when evaluating the overall percentage of Vδ2+ T cells, and the percentage of Vδ2+ T cells that produced inflammatory cytokines (IFNg, TNF) following in vitro malaria antigen stimulation." (PMID 28904345, 2017). "Plasma levels of inflammatory cytokines (IFNα, IFNγ, TNF, IL-6) and chemokines (CCL2, CCL3, CCL4, CXCL10) were significantly higher during severe malaria compared to convalescence." (PMID 27792766, 2016). "However, these IFNγ/IL-10 co-producing cells were not independently associated with protection from future malaria, and may be associated with increased risk." (PMID 24415936, 2014). "Similar findings were obtained when analyzing the “composition” (i.e. the proportion of responding cells producing IFNγ, TNFα, and/or IL10) of the malaria-specific response and duration since last malaria infection." (PMID 24415936, 2014). "Our results suggest that the functional phenotype of the malaria-specific T cell response was heavily influenced by prior malaria exposure intensity, with CD4+ T cells co-producing IFNγ and IL10 dominating this response among highly exposed children." (PMID 24415936, 2014). "The production of IFNγ and IL10 cytokines in response to malaria antigens has been shown to be important in induction and maintenance of immunity to malaria in naturally exposed population." (PMID 23533445, 2013). "Therefore, IFNγ, presented as ‘central mediator of protective immune response against malaria’, does not only point out immediate protection but could also serve as a marker for prediction of protracted protection in malaria." (PMID 22563506, 2012).
malaria (continued). "In rodent malaria models, there is strong evidence for the role of CD4+ T cells, interferon-gamma (IFN-γ) and nitric oxide contributing to the control of blood-stage parasitaemia, including those cells against the AMA1 antigen." (PMID 21698193, 2011). "PBMC and plasma collected from malaria-exposed Indonesians during infection and 7–28 days after anti-malarial therapy, were assessed for HGXPRT recognition using CFSE proliferation, IFNγ ELISPOT assay and ELISA." (PMID 19500406, 2009). "Similarly, IP-10, MCP-1, IL-6 and IFNγ were negatively correlated (P < 0.05) while TGF-β1 was positively correlated (r = 0.2; P < 0.05) with previous malaria episodes." (PMID 40690473, 2025). "Consistent with this link, Vδ2+ γδ T cells from malaria-naive adults have higher frequencies of IFNγ and TNF-producing cells in response to malaria in vitro stimulation compared to children and circulating CXCL9 was correlated with age in patients with malaria." (PMID 41027884, 2025). "In contrast, multigravid women had higher percentages of CD4+ T cells that produced TNFα in the absence of IFNγ and IL-10, and these cells were correlated with protection against malaria in pregnancy." (PMID 37634385, 2023). "However, multiple lines of evidence have shown that malaria drives the expansion of regulatory CD4 T cells, particularly Type 1 regulatory (Tr1) cells that co-produce IFNγ and IL-10 in this disease." (PMID 37968278, 2023). "This study reveals that acute blood-stage malaria promotes resistance to ONNV infection by inducing IFNg-dependent antiviral status in human and murine nonimmune cells." (PMID 35039441, 2022). "Taken together, CD4+ T cells producing IFNγ, with or without TNF co-production, are associated with parasite control in lifelong malaria-exposed individuals." (PMID 35922467, 2022). "Our study highlights IFNγ+CD4+ T and γδ T cells co-producing IFNγ and TNF as well as anti-malarial antibodies against blood-stage proteins as correlates of varying strength of naturally acquired immunity in lifelong residents of a malaria-endemic area." (PMID 35922467, 2022). "Whilst interleukin 4 (IL4) production by T helper 2 (Th2) T cells can support antibody production by B cells, IFNγ production by γδ T cells and T helper 1 (Th1) CD4+ T cells has been suggested to also play a role in mediating blood-stage protection in rodent malaria models." (PMID 33153189, 2020). "Hence, the clinical features of malaria are due to release of pro-inflammatory cytokines including TNF, interferon-gamma, IL-6, and IL-12." (PMID 33357220, 2020). "BLIMP1-mediated IL-10 production by Tr1 cells was recently reported in experimental malaria, and BLIMP1-dependent IL-10 production by Tr1 cells protected against IFNγ-dependent, TNF-mediated splenic tissue damage, but also limited the control of P. chabaudi AS blood parasitemia." (PMID 30809232, 2019). "Enhanced IFNγ production by human NK cells has been observed after RTS,S/AS01 malaria vaccination." (PMID 31533835, 2019). "Thus, the levels of both tissue and plasma IFNγ, TNFα, and IL-6 were assessed in WT and TRPV1KO mice with malaria." (PMID 31223430, 2019). "We measured Pf-specific IFNγ-, IL10-, and TNFα-producing CD4 T-cell responses by multi-parametric flow cytometry in 265 children aged 6 months to 10 years enrolled in a longitudinal observational cohort in a high malaria transmission site in Uganda." (PMID 29097996, 2017). "A more recent report using a mouse model of malaria demonstrated that therapeutic release from PD-1 exhaustion, coupled with stimulation via OX40 dramatically increased IFNγ production by Th1 cells, which destabilized Bcl-6 in established Tfh cells and resulted in defective humoral immune responses." (PMID 27812214, 2016). "Both, IFNγ and IL10, play critical roles in the immune homeostasis in acute malaria." (PMID 27802341, 2016).
malaria (continued). "The blockade showed a stronger effect on cytokine production and increased the malaria-specific IFNγ and IL10 production of all patients who exhibited a cytokine response to P. falciparum and demarcated a positive IFNγ response in one patient who was priorly unresponsive." (PMID 27802341, 2016). "Importantly, IFNγ+IL10+ Th1 cells have been shown recently to prevent immunopathology in rodent models of toxoplasmosis and malaria." (PMID 27802341, 2016). "It is highly likely that the strong antigen exposure and the cytokine milieu during acute malaria activates the IFNγ to IL10 switch, which serves as a negative feedback loop to prevent overwhelming inflammation and tissue damage." (PMID 27802341, 2016). "Severe malaria patients exhibit high levels of serum pro-inflammatory cytokines (TNF, IL-1β, IL-6, IL-8, IL-12, IFNγ) and chemokines (CCL2, CCL5, CXCL9, CXCL10), and lower levels of regulatory cytokines (IL-10, TGFβ, PGE2) compared to those with mild and asymptomatic malaria." (PMID 27792766, 2016). "The ability of MBECs to cross-present appears to be general rather than specific to malaria antigen: cross-presentation of soluble ovalbumin occurred even without IFNγ stimulation but was enhanced by it." (PMID 26046849, 2015). "Placentas from malaria-infected litters (wild-type and C5ar-/-) showed placental inflammation as indicated by increased expression of tumor necrosis factor (TNF), interferon gamma (IFNΥ), intracellular adhesion molecule-1 (ICAM-1) and monocyte chemotactic protein 1 (MCP-1, CCL2) (p < 0.05)." (PMID 26402732, 2015). "This could be explained by the high production of interferon gamma (IFN-γ) in children and resulted in higher malaria parasitemia that could lead to severe malaria." (PMID 26415939, 2015). "In RTS/S vaccine recipients, malaria-specific CD4+ T cells producing TNFα in the absence of IFNγ or IL-2 have recently been shown to correlate with protection from malaria infection." (PMID 24415936, 2014). "The predominance of IFNγ and TNFα in the CD8+ T cell response was a feature of all vaccination regimens and has previously been observed following adenoviral-vectored vaccination of BALB/c mice with recombinant malaria parasite antigens." (PMID 24304565, 2013). "On the other hand, after 6 hours of stimulus with calcium ionophore, CD56dim cells from malaria-infected patients produced the highest levels of IFNγ regardless of their clinical presentation." (PMID 22316273, 2012). "We demonstrate unequivocally that specific IFNγ responses to both stages of the malaria parasite are not only readily induced following infection, but also persist more or less undiminished over at least 14 months in the absence of further exposure." (PMID 22144890, 2011). "Previous vaccine studies using these vectors in human prime-boost regimes with much smaller inserts have demonstrated the ability to induce strong T-cell responses measured by the ex vivo IFNγ-ELISPOT and induce sterile protection on malaria challenge in some volunteers." (PMID 21501642, 2011). "We now wished to investigated whether there was a relationship between resting memory T responses, as measured by cultured IFNγ ELISPOT against TRAP and CS, and subsequent development of clinical malaria, using stored cells from the same Kenyan cohort." (PMID 18446217, 2008). "Although the heterogeneity in the response of CD40L and IFNγ suggests that our tested malaria antigens did not induce significant differences in the expression of these markers in all our participants, our panel did not include other activated induced markers, such as OX40, 4-1BB, and CD69." (PMID 40402846, 2025). "Plasma levels of IL-10 in pregnant women with malaria have been shown to be higher than those in uninfected women, and levels of malaria non-specific, IFNγ and IL-10 co-producing cells were elevated in pregnant versus non-pregnant women living in Papua New Guinea." (PMID 37634385, 2023).
malaria (continued). "Interestingly, mean serum levels of IFNγ were significantly higher in malaria-infected individuals compared to non-infected individuals (P value = 0.026)." (PMID 34557294, 2019). "Thus, T-bet+ B cells, even in the context of malaria, are likely to be a normal component of the immune compartment that becomes activated and expands, most probably in response to BCR, endosomal TLR, and IFNγ or IL-21 stimulation." (PMID 30387712, 2018). "The total IL10 response and frequency of IFNγ/IL10 coproducing cells, but not IL10 single-producing cells, were weakly associated with malaria incidence in the preceding year (rho = 0.14, p = 0.02, rho = 0.16, p = 0.01 and rho = 0.026, p = 0.67, respectively), consistent with prior reports." (PMID 29097996, 2017). "For instance, increased plasma levels of pro-inflammatory tumour necrosis factor (TNF), interferon-gamma (IFN-γ), and interleukin-1 beta (IL-1β), as well as decreased levels of anti-inflammatory cytokines, such as IL-10 and transforming growth factor beta 1 (TGF-β1), are hallmarks of severe malaria." (PMID 27357958, 2016). "We report high plasma levels of proinflammatory cytokines and chemokines (IFNγ, TNF, IL-6, CCL2, CCL3, CCL4, CXCL10) in severe malaria patients compared to baseline uninfected follow-up, which matched that of Py infection in mice in which we could conduct a temporal analysis." (PMID 27792766, 2016). "Frequencies of IFNγ/IL10 co-producing CD4+ T cells, which express the Th1 transcription factor T-bet, were significantly higher in children with ≥2 prior episodes/year compared to children with <2 episodes/year (P<0.001) and inversely correlated with duration since malaria (Rho = −0.39, P<0.001)." (PMID 24415936, 2014). "On the other hand, capsazepine treatment did not affect IFNγ release triggered by malaria." (PMID 25242870, 2014). "We measured plasma levels of soluble UA and inflammatory cytokines and chemokines (IL-6, IL-10, sTNFRII, MCP-1, IL-8, TNFα, IP-10, IFNγ, GM-CSF, IL-1β) in 470 Malian children presenting with uncomplicated malaria (UM), non-cerebral severe malaria (NCSM) or cerebral malaria (CM)." (PMID 23071567, 2012). "Analysis of basal IFNγ and TNF levels confirmed the CD56bright NK population as the main cytokine producer (p < 0.0001) in the groups affected with malaria, with the CD56dim NK cell exhibiting the highest potential of TNF production after stimulus in the acute malaria group." (PMID 22316273, 2012). "In addition, DBL3-specific IgG mid pregnancy from pregnant women with non-placental malaria at delivery induced significantly higher IFNγ and TNFα production (IFNγ: p-value = 0.0322, TNFα: p-value = 0.0184) compared to IgG from non-pregnant malaria-naïve healthy individuals." (PMID 33602987, 2021). "Although, it appears that macrophages may not be activated in natural immune response against malaria, interferon gamma(+) and IL-10(+++) secreting CD4 T cells, cytotoxic CD8 T cells, IgG secreting B cells, and NK cells are up-regulated by interferon alpha/beta in malarial infection." (PMID 24188121, 2013). "In malaria naïve subjects prior to CHMI, NK cells made up 14% of the IFNγ+ lymphocytes and this did not change during the early stages of infection." (PMID 31900030, 2020). "Recent observations in individuals naturally exposed to malaria suggest an important role for CD4+ T cell production of TNFα, with or without IFNγ, as a potential immunologic correlate of protection." (PMID 24415936, 2014). "While ex vivo IFNγ expression was below the limit of detection for all NK cell subsets, there was a significant increase in TNF production in Adaptive, but not CD56bright NK cells during malaria." (PMID 37968278, 2023). "However, we show capsazepine inhibitory effects on these populations do not affect IFNγ production in malaria, indicating that either TRPV1 may not play a role on IFNγ production or NK cells become the sole source of IFNγ once TRPV1 is blocked." (PMID 25242870, 2014).